MTOR (mechanistic target of rapamycin kinase)
Diseases named in the same sentence as MTOR in open-access papers (continued):
Sharing a sentence is not in itself a finding about the gene and the disease.
renal fibrosis (continued). "Renal fibrosis and apoptosis are inhibited by the regulation of autophagy after the suppression of mTOR and STAT3 expression." (PMID 35164031, 2022). "In conclusion, our results demonstrate that MSC treatment improves injured kidney architecture and reduces renal fibrosis by autophagic inhibition and by interfering with the mTOR signaling pathway via excreted exosomes containing mainly miRNA-122a." (PMID 35859725, 2022). "The aim of this study was to investigate the beneficial effect of mTOR/STAT3 ODN via the regulation of autophagy appearance on unilateral ureteral obstruction (UUO)-induced renal fibrosis." (PMID 35164031, 2022). "We also determined the role of mTOR signaling and changes in the autophagic response in renal fibrosis." (PMID 35859725, 2022). "It is reported that let-7i-5p promotes renal fibrosis by targeting tuberous sclerosis complex subunit 1 (Tsc1) to activate the mammalian target of rapamycin (mTOR) signaling in UUO mice." (PMID 36091385, 2022). "Similar results were obtained in the present study via Western blot analysis, confirming that the expression levels of p-Akt, p-PI3K, and p-mTOR decreased in the UUO-induced renal fibrosis group." (PMID 33806080, 2021). "MSCs-exosomes increased autophagy markers mechanistic target of rapamycin (mTOR), Beclin-1 as well as light chain-3 (LC-3) to activate autophagy, thus improve renal fibrosis." (PMID 34163437, 2021). "Studies have shown that renal fibrosis can be alleviated by inhibiting the phosphoinositide 3‐kinase/Akt/mTOR signaling pathway." (PMID 34029013, 2021). "Several processes that are regulated by the mTOR pathway, such as autophagy, epithelial-mesenchymal transition (EMT), and endoplasmic reticulum (ER) stress, are tightly associated with renal fibrosis." (PMID 33634104, 2020). "The ROC curve showed that mTOR can diagnose IgAN at a cut-off value of 0.930 with the sensitivity of 90.2% and specificity of 73.8% and renal fibrosis at a cut-off value of 0.301 with the sensitivity of 71.7% and specificity of 64.8%." (PMID 31485275, 2019). "Our research indicated that urinary mTOR mRNA can serve as a potential biomarker to diagnose renal fibrosis." (PMID 31485275, 2019). "Our study revealed that urinary mTOR mRNA expression was a potential biomarker for IgAN and renal fibrosis." (PMID 31485275, 2019). "Firstly, the current study is a discovery study focused on IgAN; if urinary mTOR expression can serve as a biomarker of renal fibrosis in other types of CKD needs to be further studied." (PMID 31485275, 2019). "Stepwise multivariate logistic regression analysis showed that the relative expression of urinary mTOR strongly correlated with the severity of renal fibrosis (OR 10.325, 95% CI: 1.147-50.621, P < 0.001)." (PMID 31485275, 2019). "Urinary mTOR mRNA expression was a potential biomarker for diagnosis of IgAN and renal fibrosis in IgAN patients." (PMID 31485275, 2019). "Accordingly, this study was designed to determine the expression of urinary mTOR via qPCR to indicate renal fibrosis." (PMID 31485275, 2019). "Blockade of the CRP signaling with an anti-CD32b antibody or Smad3 signaling with a specific inhibitor (SIS3) was able to inhibit mTOR signaling, thereby attenuating renal fibrosis including mesangial expansion under high CRP conditions in vivo and in vitro." (PMID 27221338, 2016). "The functional importance for the CD32b-Smad3-mTOR pathway in renal fibrosis was further demonstrated by the ability of rapamycin to inactivate the mTOR signaling, thereby inhibiting CRP and high glucose-induced CTGF and collagen I expression." (PMID 27221338, 2016). "CRP alone was able to enhance Smad3-mTOR interaction and induce mTOR/S6K activation and renal fibrosis." (PMID 27221338, 2016). "Despite that inhibition of the mTOR pathway can attenuate renal fibrosis in animal models, application of rapamycin in patients with CNIs did not result in consistent beneficial effects." (PMID 25285155, 2014).
renal fibrosis (continued). "This study, for the first time, clarified that which cell types have mTOR activation in renal fibrosis and where rapamycin works on to protect the kidney." (PMID 22470459, 2012). "Additionally, mitophagy can inhibit the expression of fibrosis-related proteins through the AMPK/mTOR signaling pathway, ultimately preventing the progression of renal fibrosis." (PMID 40305351, 2025). "Moreover, excessive production of reactive oxygen species due to oxidative stress can mediate epithelial–mesenchymal transition and inhibit the PI3K/Akt/mTOR pathway in renal tubular epithelial cells, promoting renal fibrosis." (PMID 39717716, 2025). "Particularly during EMT progression, mTOR activation enhances cells’ capacity to synthesize extracellular matrix proteins which are critical for phenotypic transformation and further aggravation of renal fibrosis." (PMID 39028478, 2025). "As a result of hyperglycemic stimulation of PI3K and inhibition of PTEN, the Akt/mTOR pathway is activated, leading to the development of DN through abnormal podocyte autophagy, renal fibrosis, enlargement of the mesangial matrix and thickening of the basement membrane." (PMID 38747698, 2024). "Gal-3 knockdown may enhance autophagy by inhibiting the Gal-3/Akt/mTOR pathway, which helps ameliorate renal fibrosis." (PMID 38769548, 2024). "In addition, further research showed that the PI3K/mTOR‐mediated autophagy pathway was involved in C. cicadae‐mediated effects on renal fibrosis in MRL/lpr mice." (PMID 38270299, 2024). "In addition, ROS-induced senescence was shown to require the mammalian target of rapamycin (mTOR) activation, and accumulated IS promoted renal fibrosis via mTOR under CKD conditions." (PMID 37760849, 2023). "Accordingly, in the present study, we found that ASIV increased the expression of ALDH2 and inhibited autophagy by activating the AKT/mTOR pathway in the mitigation of renal fibrosis, which was further validated by small RNA interference to knock down ALDH2 in TGF-β-induced HK-2 cells." (PMID 37443810, 2023). "Furthermore, we found that MSC-derived exosomes mediate miRNA-122a to relieve renal fibrosis in HK-2 cells in response to TGF-β1 through the regulation of mTOR signaling and autophagy." (PMID 35859725, 2022). "Histopathological examinations were performed after MK-2206 intervention, and the degree of renal fibrosis, as well as the expression of Akt/mTOR pathway-related proteins, were evaluated by immunohistochemical staining, immunofluorescence staining, and Western blot." (PMID 36359901, 2022). "Therefore, the mTOR signaling pathway can be a new therapeutic target for preventing the progression of renal fibrosis and inflammation." (PMID 36232665, 2022). "We hypothesized that HDHW could modulate the activity of the IGF-1/PI3K/Akt/mTOR pathway, inhibits autophagy and ameliorate renal fibrosis." (PMID 36160409, 2022). "Therefore, emodin enhances podocyte autophagy, inhibits apoptosis, and alleviates renal fibrosis mainly by regulating the AMPK/mTOR signaling pathway." (PMID 36105187, 2022). "PI3K/AKT/mTOR signaling pathway is a crucial pathway in renal fibrosis." (PMID 32372953, 2020). "In addition, p68-mediated activation of the PKD-associated pathways, ERK, mTOR, Rb and TGF-β1, should increase cystic renal epithelial cell proliferation and renal fibrosis, resulting in cystogenesis." (PMID 32724471, 2020). "Urinary mTOR mRNA detection served as a noninvasive detection of IgAN and renal fibrosis." (PMID 31485275, 2019). "In summary, our study demonstrated that detection of urinary mTOR mRNA could well predict renal fibrosis severity in IgAN, which suggested that this will serve as a novel independent noninvasive biomarker to monitor the progression of kidney fibrosis in IgAN." (PMID 31485275, 2019). "The urinary mTOR expression level has diagnosis value for IgAN and renal fibrosis." (PMID 31485275, 2019).
renal fibrosis (continued). "Also, fasting abrogated ERK1/2 and mTOR signaling, both playing important roles in renal fibrosis development." (PMID 31443530, 2019). "Previous studies also indicated that mTOR played a key role in renal fibrosis." (PMID 31485275, 2019). "Finally, we also found that CRP induced renal fibrosis through a CD32b-Smad3-mTOR pathway because blocking mTOR signaling with rapamycin inhibited CRP-induced CTGF and collagen I expression." (PMID 27221338, 2016). "Secondly, persistent mTOR activation in these effectors at an extended stage of injury, however, might be maladaptive by promoting chronic inflammation and ultimately renal fibrosis." (PMID 22470459, 2012). "Taken together, our studies revealed that rapamycin could ameliorate renal fibrosis by inhibiting the mTOR signaling in activated myofibroblasts." (PMID 22470459, 2012). "To determine whether the tubular epithelial cells remain potential targets of rapamycin in the progression of renal fibrosis, we studied the relationship between tubular fibrogenic activity and mTOR signaling." (PMID 22470459, 2012). "In a murine model of renal fibrosis (UUO), EMT, hypoxia, apoptosis, genes downregulated in response to ultraviolet (UV) radiation, G2/M checkpoint of cell division cycle, and cell signaling (Notch and PI3K/Akt/mTOR) pathways were the most enriched in the MSigDB hallmark gene sets analysis." (PMID 38804362, 2024). "By integrated network pharmacology, transcriptomic analysis, and pharmacological assessment, we predicted and confirmed that the therapeutic mechanism of YSPDP in addressing 5/6 SNx-induced renal fibrosis may involve inhibition of the PI3K/AKT/mTOR signaling pathway." (PMID 39669205, 2024). "The mechanism of HDHW ameliorating renal fibrosis may be that HDHW inhibits autophagy by upregulating IGF-1 expression, promoting the binding of IGF-1 to IGF-1R, and activating the autophagy-related pathway PI3K/Akt/mTOR, which in turn attenuate renal fibrosis." (PMID 36160409, 2022). "However, mTOR/STAT3 ODN suppressed UUO-induced renal fibrosis and inflammation." (PMID 35164031, 2022). "Therefore, targeting the IGF-1/PI3K/Akt/mTOR pathway to inhibit the sustained activation of autophagy during renal fibrosis may be an appropriate approach for the treatment of renal fibrosis." (PMID 36160409, 2022). "The miRNA regulatory network genes may participate in the regulation of podocyte autophagy, lipid metabolism, and renal fibrosis through mTOR, PDGFR-β, LKB1, and VEGF/VEGFR signaling pathways, thereby affecting the occurrence and development of membranous nephropathy." (PMID 34824764, 2021). "It remained unknown if mTOR can act as a biomarker for IgAN, especially for renal fibrosis." (PMID 31485275, 2019). "Additionally, urinary mTOR mRNA expression also correlated with renal fibrosis in IgAN." (PMID 31485275, 2019). "In vivo, pirfenidone treatment in Pkd1RC/RC mice reduced renal fibrosis, collagen deposition, myofibroblast accumulation, pro-fibrotic gene expression and decreased TGF-β/SMAD3 and mTOR signaling." (PMID 40909512, 2025). "mTOR is subsequently activated through p-AKT, and its aberrant activation disrupts immune balance, promotes autoimmune responses, induces renal fibrosis, inhibits autophagy, and contributes to kidney damage." (PMID 40573311, 2025). "Excessive activation of the mTOR signaling pathway is closely related to the progression of CKD, particularly in relation to glomerular hypertrophy and renal fibrosis." (PMID 40289841, 2025). "Previous studies have demonstrated that PI3K/AKT/mTOR signaling is abnormally activated in HUA, contributing to renal fibrosis." (PMID 40431419, 2025). "Meanwhile, Qidan Dihuang Decoction protects against renal fibrosis in DKD by inhibiting EMT and inflammatory responses via the p38MAPK and AKT/mTOR signaling pathways." (PMID 40337513, 2025).
renal fibrosis (continued). "Phosphorylation of S6 and 4E-BP1 by mTOR enhances translational capacity, induces cell proliferation, protein synthesis, EMT induction and renal fibrosis." (PMID 41323737, 2025). "In conclusion, metformin combined with rapamycin decreased proteinuria, improved renal fibrosis and podocyte autophagy via AMPK/mTOR pathway in IMN rats." (PMID 37702819, 2023). "TGF-β1 is a key mediator in the development of renal fibrosis, and our study demonstrated that TGF-β1 activated the PI3K-Akt-mTOR pathway and participated in pericyte differentiation by increasing glycolysis." (PMID 37179292, 2023). "In DKD models, it has been shown that blocking KCa3.1 reverses diabetes-inhibited tubular autophagy and thus improves renal fibrosis, which is mediated by inhibiting the activation of the PI3K/Akt/mTOR signaling pathway." (PMID 36105212, 2022). "This study proved that the inhibition of mTOR and STAT3 expression has a therapeutic effect on preventing renal fibrosis." (PMID 35164031, 2022). "The results of the study showed that the inhibitory effect of HDHW on autophagy and renal fibrosis was altered after blocking the binding of IGF-1 to IGF-1R, and the phosphorylation processes of PI3K, Akt, and mTOR were also blocked." (PMID 36160409, 2022). "This suggests that HDHW activates the IGF-1/PI3K/Akt/mTOR signaling pathway, a key pathway in regulating autophagy, which further supports the regulatory effect of HDHW on autophagy in renal fibrosis rats." (PMID 36160409, 2022). "In conclusion, we found in the present study that YSHS inhibited progression of DN via ameliorating renal fibrosis and preserving the integrity of the kidney filtration barrier, and the PI3K/AKT/mTOR pathway played a pivotal role in it." (PMID 35935814, 2022). "Current studies suggest that TGF-β helps protect mTOR from degradation by inhibiting Deptor (an inhibitor of mTOR) in a Smad-dependent manner, and also activates mTOR1 and mTOR2 by inducing the PI3K/AKT signaling pathway in renal fibrosis." (PMID 36148005, 2022). "PI3K/AKT signaling pathway is the upstream regulator of the mTOR-signaling pathway, a critical process in cellular metabolism; an existing study elucidated the involvement of the PI3K/AKT/mTOR axis with renal fibrosis." (PMID 34869303, 2021). "In the same context, pharmacological inhibitors of the PI3K/Akt/mTOR pathway, LY294002 and triptolide, were found to alleviate hepatic and renal fibrosis, respectively, by enhancing autophagy." (PMID 34879114, 2021). "However, if urinary mTOR RNA expression is related to renal fibrosis is unknown." (PMID 31485275, 2019). "IDO activity inhibits the tryptophan sufficiency signal that stimulates mTOR, an important pathway to induce EMT and consequently renal fibrosis." (PMID 28877670, 2017). "Finally, the authors demonstrated that CRP promoted renal fibrosis by increasing CTGF and collagen I expression, an effect that was blocked by the mTOR inhibitor rapamycin, confirming the critical role of the CD32b–Smad3–mTOR axis." (PMID 41373439, 2025). "In the in vitro and in vivo experiments of DKD, Fucoidan has excellent ability to regulate AMPK/mTOR pathway, which can be targeted to inhibit the accumulation of ECM and GBM to alleviate renal fibrosis, and also inhibit the activation of NLRP3 and reduce podocyte pyroptosis." (PMID 39707216, 2024). "In addition to the canonical TGF-β/Smad signaling pathway, TGF-β1 can also jointly mediate renal fibrosis by activating other signaling pathways, such as the MAPK and PI3K/Akt/mTOR pathways." (PMID 36105187, 2022). "For renal fibrosis, it was reported that the Rictor/mTORC2 signaling pathway mediates TGF-β1-induced fibroblast activation, and the TGFβ-induced synthesis of the extracellular matrix is mediated by the Akt/mTOR pathway." (PMID 36359901, 2022).
renal fibrosis (continued). "Although previous studies have shown a close relationship between the Akt/mTOR pathway and renal fibrosis, no studies have shown that MK-2206 can be used for the therapy of renal fibrosis." (PMID 36359901, 2022). "Compare to PCA, rapamycin reduces renal fibrosis by inhibiting mTOR signalling, but this is not observed with PCA, thus, the mechanism of PCA still needs to be identified." (PMID 35758295, 2022). "Collectively, these results suggest a renoprotective role of AD-114 as it inhibited the chemotactic function of CXCR4 as well as blocked CXCR4 downstream p38 MAPK and PI3K/AKT/mTOR signaling, which establish a therapeutic strategy for AD-114 targeting CXCR4 to limit renal fibrosis." (PMID 35015734, 2022). "Preclinical models show that both KD and IF are effective in inhibiting the mTOR/AMPK pathway, cystogenesis, and renal fibrosis, and that these effects are specifically induced by ketosis, as demonstrated by the inhibition of PKD progression by the administration of b-hydroxybutyrate." (PMID 35811945, 2022). "In conclusion, our study shows that YJHD further inhibits the mTOR pathway and promotes autophagy by regulating the activity of the PI3K/Akt and AMPK pathways, thereby improving podocyte injury, protecting renal function, and reducing renal fibrosis." (PMID 33912044, 2021). "The experimental validation results demonstrated that NE-THCQ might inhibit the inflammatory processes, reduce ECM deposition and reverse EMT via PI3K/AKT/mTOR and HIF-1α/VEGF signaling pathways to exert its effect against renal fibrosis." (PMID 32372953, 2020). "Autophagy activation accompanied with renal fibrosis in rats with adenine-induced renal tubular injury, and both autophagy and renal fibrosis could be alleviated by rhein through the AMPK/mammalian target of rapamycin (mTOR) signaling pathway." (PMID 33854427, 2020). "Tripterygium glycoside and triptolide could alleviate renal fibrosis involving the miR-141-3p/phosphatase and tensin homolog/AKT/mTOR pathway, TGF-β1/Smad3 pathway and TLR4/NF-κB pathway." (PMID 33854427, 2020). "Emerging evidence also implicates extracellular signal-regulated kinase 1/2 (ERK1/2) and the mechanistic target of rapamycin (mTOR), which operate downstream of TGF-β1 signaling, in renal fibrosis development, thus expanding our understanding of CKD pathophysiology." (PMID 31443530, 2019). "They regulate multiple signaling pathways such as Wnt/β-catenin, TGF-β1/Smad, Akt/mTOR, CX3CL1-RAF/MEK/ERK, mTORC1/p70S6K, SIRT1-NF-κB, and interfere with different cytokine or inflammatory factors expression to regulate the development and progression of renal fibrosis." (PMID 36160409, 2022). "Our previous work showed that AP-2β induces expression of KCTD1 that functions as a repressor of β-catenin signaling and that mice lacking KCTD1 develop progressive DCT defects and renal fibrosis accompanied by β-catenin hyperactivation and downstream profibrogenic mTOR activation." (PMID 35468900, 2022). "Finally, our findings suggest that NE-THCQ may inhibit renal fibrosis progression mainly by regulating the inflammatory process, reversing EMT and decreasing ECM deposition through PI3K/AKT/mTOR and HIF-1α/VEGF signaling pathways." (PMID 32372953, 2020). "Based on the AMPK/mTOR signaling pathway, we investigated if metformin combined with rapamycin could activate autophagy to improve pathological changes in IMN model rats, including inflammatory infiltration of macrophages, secretion of inflammatory factors, and renal fibrosis." (PMID 37702819, 2023). "In summary, the results of this study show that ASIV effectively treats renal fibrosis by alleviating EMT procession and G2/M arrest in vivo and in vitro, and this may be due to the ASIV-induced upregulation of the expression of ALDH2, which inhibits autophagy by regulating the AKT/mTOR pathway." (PMID 37443810, 2023).
renal fibrosis (continued). "The PI3K/Akt/mTOR pathway is a non-canonical TGF-β signalling pathway that contributes to the induction of epithelial to mesenchymal transition (EMT) and renal fibrosis." (PMID 41323737, 2025).